KLF6 (KLF transcription factor 6)
Diseases named in the same sentence as KLF6 in open-access papers (continued):
Sharing a sentence is not in itself a finding about the gene and the disease.
renal fibrosis (3 papers, 2022 to 2023). A final common manifestation of a wide variety of chronic kidney diseases characterized by glomerulosclerosis and tubulointerstitial fibrosis. "Gain- and loss-of-function studies in vivo and in vitro were performed to assess the effect of BMSC-derived EVs (BMSC-EVs), which contained miR-181d, on KLF6, NF-κB, and renal fibrosis." (PMID 35672285, 2022). "We verified the effect of EV-transferred miR-181d on UUO-induced renal fibrosis in rats as a result of the activation of the KLF6/NF-κB signaling pathway." (PMID 35672285, 2022). "In conclusion, miR-181d transferred by BMSC-EVs can attenuate UUO-induced renal fibrosis in rats by inactivating the KLF6-dependent NF-κB signaling pathway." (PMID 35672285, 2022). "Nevertheless, further studies are required to explore the specific mechanism regarding KLF6-mediated NF-κB signaling pathway as well as the effect of the NF-κB signaling pathway in renal fibrosis." (PMID 35672285, 2022). "In renal tissue, previous work shows that KLF6 is upregulated in periglomerular activated fibroblasts during the development of renal fibrosis, suggesting its role in the process of renal tissue remodeling." (PMID 34967261, 2022). "However, in our study, we determined the expression difference of miR-181d and KLF6 in renal biopsy samples from renal fibrosis patients and healthy controls through clinical case analysis, and the results were more reliable." (PMID 35672285, 2022). "Based on this information, we tested whether miR-181d-containing EVs derived from BMSCs could suppress renal fibrosis by inhibiting KLF6 and the NF-κB signaling pathway." (PMID 35672285, 2022). "In addition, KLF6 was found to be overexpressed in renal fibrosis in the GSE36496 dataset, a GEO database profile." (PMID 35672285, 2022). "Additionally, Western blot analysis and RT-qPCR demonstrated that an inhibitor of the NF-κB signaling pathway, BAY-11-7082, could counteract KLF6 function in renal fibrosis." (PMID 35672285, 2022). "Furthermore, we found that KLF6-activated NF-κB pathway promoted renal fibrosis." (PMID 35672285, 2022). "Krüppel-like factor 6 (KLF6) was speculated as a target of miR-181d, and is a DNA-binding protein that contains three zinc-fingered motifs important in the regulation of renal fibrosis pathogenesis." (PMID 35672285, 2022).
Sepsis (3 papers, 2020 to 2025). Sepsis is defined as life-threatening organ dysfunction caused by a dysregulated host response to infection. "NFκB1 and KLF6 synergistically amplify the inflammatory response in sepsis." (PMID 41303672, 2025). "CircMTO1 overexpression could attenuate AKI development by sponging miR-337 and regulating KLF6 expression, which may provide new ideas for evaluation the pathogenesis and the treatment of sepsis-induced AKI." (PMID 32157506, 2020). "CircMTO1 overexpression could attenuate AKI development by sponging miR-337 and regulating KLF6 expression, which may provide new ideas for the evaluation of the pathogenesis and the treatment of sepsis-induced AKI." (PMID 32157506, 2020).
acute liver failure (2 papers, 2017 to 2023). Rapid deterioration of liver function causing encephalopathy and coagulopathy. "Particularly, hepatic KLF6 is elevated in patients with acute liver failure and in mice subjected to CCL4 or acetaminophen administration." (PMID 36902112, 2023). "KLF6 contributes to the pathogenesis of drug-induced hepatotoxicity as well as acute liver failure, making it an attractive pharmacological target to alleviate hepatotoxicity." (PMID 36902112, 2023). "Here we explore the role of KLF6 in acute liver injury models in mice, and in patients with acute liver failure (ALF)." (PMID 28808340, 2017).
focal segmental glomerulosclerosis (2 papers, 2024 to 2025). A renal disorder characterized by sclerotic lesions in the glomeruli. "Specifically in the podocyte, KLF6 is a key regulator of mitochondrial function and the conditional loss of Klf6 in podocytes reduces mitochondrial complex IV assembly, which exacerbates glomerular injury in murine models of Focal Segmental Glomerulosclerosis (FSGS) and DKD9,10." (PMID 39271683, 2024).
glomerular disease (2 papers, 2023 to 2024). "KLF4, KLF6, and KLF15 were also shown to be expressed in glomerular podocytes, and their protein expression levels were significantly reduced in injured podocytes in proteinuria glomerular diseases 31-35." (PMID 36632460, 2023).
hepatopulmonary syndrome (2 papers, 2019 to 2024). Hepatopulmonary syndrome (HPS) is a lung disease characterized by widening of arteries and veins (dilatation) in the lungs in people who have chronic liver disease. "Some studies have reported that Krüppel-like factor 6 (KLF6) mediates pulmonary angiogenesis in an experimental rat model of hepatopulmonary syndrome and is exacerbated by BMP9." (PMID 39199400, 2024).
liver disease (2 papers, 2016 to 2023). "In addition to KLF6, other KLF proteins also play important roles in different liver diseases." (PMID 37391422, 2023).
maturity-onset diabetes (2 papers, 2024 to 2025). "Furthermore, among the 18 KLF proteins, only KLF1, KLF6, and KLF11 have MIM phenotype numbers, associating them with dyserythropoietic anemia (613673), prostate (176807) and gastric (613659) cancers, and maturity-onset diabetes of the young, type VII (610508), respectively." (PMID 39202416, 2024).
multiple sclerosis (2 papers, 2016 to 2024). A progressive autoimmune disorder affecting the central nervous system resulting in demyelination. "Third, scRNA-seq analysis on human TH17 cells showed that KLF6 is expressed in TH17 cells in individuals with small intestinal chronic inflammation such as Crohn’s disease but not in other TH17 cell-mediated pathologies such as multiple sclerosis or ulcerative colitis." (PMID 39060651, 2024).
periodontitis (2 papers, 2021 to 2024). An acute or chronic inflammatory process that affects the tissues that surround and support the teeth. "At present, the molecular mechanism that miR-543-3p regulates the expression of KLF6 and affects the occurrence and development of periodontitis." (PMID 33955459, 2021). "We performed the present study to investigate which role the miR-543-3p/KLF6 axis plays in periodontitis, and found that KLF6 functions in the progression of periodontitis by modulating miR-543-3p." (PMID 33955459, 2021). "Taken together, miR-543-3p play a critical role in the progression of periodontitis by modulating the expression of KLF6." (PMID 33955459, 2021). "In summary, our research demonstrated that miR-543-3p participates in the occurrence and progression of periodontitis by targeting KLF6." (PMID 33955459, 2021). "Our study suggested Ropinirole may be a promising anti-inflammatory agent for periodontitis treatment, and NAT10 and KLF6 may be potential targets to treat periodontitis." (PMID 38689229, 2024). "Furthermore, our research demonstrated Kruppel-like factor 6 (KLF6) served as a direct downstream target of miR-543-3p to play a vital role in periodontitis." (PMID 33955459, 2021). "And KLF6 overexpression attenuated the anti-inflammatory effect of miR-543-3p in periodontitis." (PMID 33955459, 2021). "The function of miR-543-3p/KLF6 was determined to patriciate in the occurrence of inflammation in the periodontal ligament cells (PDLCs) induced by LPS, providing a new insight for the clinical treatment of periodontitis." (PMID 33955459, 2021). "Furthermore, miR-543-3p could down-regulate inflammation and inhibit periodontitis by targeting KLF6." (PMID 38689229, 2024). "Simply put, these findings suggest that miR-543-3p could down-regulate inflammation and inhibit periodontitis by targeting KLF6, and it provides a new insight into the molecular mechanism of periodontitis, which may be helpful for the early diagnosis and treatment of this disease." (PMID 33955459, 2021). "Therefore, KLF6 may be a target for periodontitis treatment, and the interaction relationship between NAT10 and KLF6 in HGFs was investigated, and the results suggested that NAT10 can elevate the mRNA levels of KLF6 and the ac4C mRNA levels of KLF6." (PMID 38689229, 2024).
rectal cancer (2 papers, 2021 to 2022). A primary or metastatic malignant neoplasm that affects the rectum. "KLF3 and KLF6 expressions were favourably related to the infiltration levels of all immune cell types except CD4+ T cells in rectal cancer." (PMID 35345512, 2022).
retinoblastoma (2 papers, 2019 to 2022). A malignant tumor that originates in the nuclear layer of the retina. "Mitochondrial apoptosis was also detected as an underlying mechanism of action of artesunate in retinoblastoma (WERI-Rb1) cells and Sprague-Dawley rats through the up-regulation of Kruppel-like factor 6 (KLF6)." (PMID 35267408, 2022).
acute promyelocytic leukemia (1 paper, 2013). An aggressive form of acute myeloid leukemia (AML), characterized by arrest of leukocyte differentiation at the promyelocyte stage, due to a specific chromosomal translocation t(15;17) in myeloid cells. "Their study showed that KLF6 expression was induced during the neutrophil differentiation of acute promyelocytic leukemia (APL) cells and that inhibiting KLF6 attenuated their differentiation." (PMID 23977008, 2013).
alveolar capillary dysplasia (1 paper, 2026). "DisGeNET and spatial transcriptomic analyses of control and PAH lungs reveal elevated KLF6 in PAH endothelium, endothelial progenitor cells, and PAH with alveolar capillary dysplasia." (PMID 42298125, 2026).
amyotrophic lateral sclerosis (1 paper, 2017). Amyotrophic lateral sclerosis (ALS) is a neurodegenerative disease characterized by progressive muscular paralysis reflecting degeneration of motor neurons in the primary motor cortex, corticospinal tracts, brainstem and spinal cord. "A recent study showed a significant up-regulation of MEF2C and MEF2D mRNA levels in both sporadic and SOD1+ amyotrophic lateral sclerosis (ALS) patients detected by gene expression analysis, and a down-regulation of their targets, BDNF, KLF6, and RUFY3." (PMID 29340119, 2017).
Ataxia (1 paper, 2016). Ataxia refers to impaired coordination of voluntary muscle movement. "Our data show that gp130/Stat3-driven Klf6 induction promotes differentiation, whereas mice with lineage-selective inactivation of Klf6 or upstream Stat3 signaling show profound failure of CNS myelination, which results in tremor, ataxia, and death." (PMID 27213272, 2016).
B-cell lymphomas (1 paper, 2024). "Kruppel Like Factor 6 (KLF6; C−A− quadrant) is a key part of recruiting macrophages to the inflammation site and the immune response subsequent success, which is lacking in cancers, including B-cell lymphomas." (PMID 39336806, 2024).
bacterial sepsis (1 paper, 2025). "The eight differentially expressed genes (DEGs) as key diagnostic markers for bacterial sepsis: FTH1, B2M, NAMPT, KLF6, SRGN, S100A6, S100A9, and S100A8." (PMID 41303672, 2025).
bladder cancer (1 paper, 2021). "The alteration frequency of KLF6 in bladder cancer was the highest, which had a total of 8.76% alteration in 411 cases." (PMID 34776953, 2021).
Breast Tumor (1 paper, 2010). "Moreover, this KLF6 expression pattern tends to be associated with small size and stage I ductal breast tumors, as well as with axillary lymph node metastasis." (PMID 20126619, 2010). "More importantly, seventy-one percent (15/21) of the ductal breast tumor tissues sub-population with both nuclear KLF6 distribution and ERBB2-overexpression also were positive for Estrogen Receptor alpha." (PMID 20126619, 2010). "Immunohistochemical assays revealed that epithelial cells of the whole breast tumor tissues population developed a specific staining for KLF6." (PMID 20126619, 2010). "Nuclear localization of KLF6 together with an ERBB2-overexpression suggests that KLF6 function is associated with the malignant phenotype, grow and development of this type of breast tumor." (PMID 20126619, 2010). "In this regard, 86% (6/7) of stage I-ERBB2 overexpressing ductal breast tumors have positive nuclear stain for KLF6." (PMID 20126619, 2010). "KLF6 is preferentially expressed in 91% (10/11) of small ERBB2 overexpressing ductal breast tumors, while the expression percentage is homogeneous in the remaining tumor size subpopulation." (PMID 20126619, 2010). "In contrast to other type of tumor tissues, KLF6 expression was confined in a large extent and almost exclusively in the nuclear compartment in a high percentage of these breast tumors tissues (L1)." (PMID 20126619, 2010). "Nuclear localization of KLF6 observed in cells of breast tumor tissue sections is in line with high expression levels of ERBB2." (PMID 20126619, 2010). "To further understand the impact of nuclear expression of KLF6 in ERBB2-overexpressing ductal breast tumors we compare this stain pattern respect to clinico-pathological parameter such as tumor stage, histological grade and size, and lymph node involvement." (PMID 20126619, 2010). "An independent analysis performed by RNA microarrays hybridization of samples obtained from a distinct breast tumor group indicated a direct correlation between the expression level of klf6 and HER-2/neu genes." (PMID 20126619, 2010). "Following, the KLF6 nuclear localization was related to the HER2-ERBB2 overexpression in ductal breast tumor tissues." (PMID 20126619, 2010). "In focus on the ERBB2-positive ductal breast tumor population, the results presented in this work demonstrated that there is a significant percentage of tissues that express nuclear KLF6." (PMID 20126619, 2010). "More importantly, 57.6% (34/59) of the analyzed breast tumors tissues whole population exhibited positive nuclear immunostain for KLF6." (PMID 20126619, 2010). "In this sense, nuclear distribution of KLF6 was observed in 100% (7/7) in ERBB2 overexpressing ductal breast tumors with histological grade 1." (PMID 20126619, 2010). "Following, the KLF6 immunostaining was also positive in the cytoplasmic compartment of the complete breast tumor tissues population." (PMID 20126619, 2010). "Overall these observations clearly suggest that the nuclear expression of KLF6 frequently occurs in ERBB2-overexpressing ductal breast tumor cases, which is in line with tumor aggressiveness." (PMID 20126619, 2010). "Interestingly, a significant subpopulation (chi-square p = 0.001, Pearson p<0.001) of twenty-five breast tumor tissues overexpressing HER2-ERBB2 were positive for nuclear KLF6." (PMID 20126619, 2010). "This analysis clearly suggests that KLF6 may be nuclear localized in aggressive breast tumor tissues determined by the HER2-ERBB2 overexpression status." (PMID 20126619, 2010). "Clinicopathological parameters of ERBB2-overexpressing ductal breast tumors and nuclear KLF6." (PMID 20126619, 2010). "Interestingly, KLF6 was extensively detected in the nucleus of HER-2/ERBB2-overexpressing breast tumor cells whereas it was mainly cytoplasmic in the normal tissue counterpart." (PMID 20126619, 2010).
Breast Tumor (continued). "In addition, regardless its sub-cellular distribution, the global klf6 gene expression seems to be augmented in accordance with the HER2/neu gene expression level in this type of ERBB2-overexpressing ductal breast tumors." (PMID 20126619, 2010). "Interestingly, though ERBB2 expression level varied in different breast tumor samples, tissues having a nuclear localization of KLF6 show higher expression of ERBB2, as observed in both tissues lots." (PMID 20126619, 2010). "Interestingly, the greater percentage of metastatic (positive) lymph nodes occurred in patients with ERBB2 overexpressing ductal breast tumors showing in addition positive nuclear stain for KLF6 (88%, 7/8), and represent the major subpopulation of cases with analyzed axillary lymph nodes." (PMID 20126619, 2010). "Following we examined the Estrogen Receptor alpha-α status depending on nuclear KLF6 distribution and ERBB2-overexpression in ductal breast tumor tissues." (PMID 20126619, 2010). "Apart of the KLF6 expression analysis, immunohistochemical assays were performed to determine the HER2-ERBB2 aggressiveness marker status in the studied breast tumor population." (PMID 20126619, 2010). "Next, to evaluate the significance between the nuclear KLF6 and HER2-ERBB2 overexpression, immunostain intensities of both proteins were estimated for each breast tumor tissue." (PMID 20126619, 2010). "Data are consistent with a preferential localization of KLF6 in the nuclear compartment of early stage and small HER2-ERBB2 overexpressing ductal breast tumor cells, also presenting lymph node metastatic events." (PMID 20126619, 2010). "Analysis of the nuclear KLF6 expression along with the Estrogen receptor alpha status and HER2-ERBB2 overexpression in breast tumor tissues." (PMID 20126619, 2010). "For the remaining tumor tissues, only sixteen breast tumor tissues were single positive (nine for nuclear KLF6, and seven for HER2-ERBB2), and eighteen were negative for both immunostains." (PMID 20126619, 2010). "ERBB2 overexpressing ductal breast tumors did not revealed a preferential relationship of histological grades and nuclear KLF6 expression." (PMID 20126619, 2010). "Analysis of KLF6 and HER2-ERBB2 proteins in breast tumor tissues." (PMID 20126619, 2010).
Cerebral ischemia (1 paper, 2021). Restriction of arterial blood supply to the brain associated with insufficient oxygenation to support the metabolic requirements of the tissue. "Taken together, our data revealed that Pimavanserin protected against cerebral ischemia injury by regulating the BBB integrity in a KLF6-dependent manner." (PMID 34605354, 2021). "In conclusion, our data revealed that Pimavanserin protected against cerebral ischemia injury by maintaining BBB integrity in a KLF6-dependent manner." (PMID 34605354, 2021). "In addition, the effects of Pimavanserin on the expression level of Claudin 5 and endothelial permeability were both abolished by the knockdown of KLF6, indicating that the protective effect of Pimavanserin in cerebral ischemia injury is mediated by KLF6." (PMID 34605354, 2021).
cervical tumor (1 paper, 2017). "After incubation with either washed human platelets or collagen-related peptide (CRP) activated platelet releasates, expression of KLF6 in the HeLa cervical tumor cell line was markedly reduced." (PMID 29152072, 2017).